CCL17 (C-C motif chemokine ligand 17)
Diseases named in the same sentence as CCL17 in open-access papers (continued):
Sharing a sentence is not in itself a finding about the gene and the disease.
tumor (continued). "These correlations change with time, with early low expression of CCL17, CXCL1 and CCL2 eventually promoting myeloid cell development that maintains/promotes larger tumours." (PMID 35226704, 2022). "A protein array on a lysate of tumors treated with MTX alone displayed a more than 1.5 fold increase of CCL17, CXCL11, CD160 and CXCL10, as compared to control tumor lysate." (PMID 36397148, 2022). "Summary of the involvement of CCL2, CCL17, and CCL22 in different health problems in the cases of pain, immunity, and tumor studies." (PMID 36555280, 2022). "In BCC, the expressions of PDGFR and prolyl-4-hydroxylase mRNA were augmented among the CAF activation markers, leading to increased CAF-related chemokines CCL17, CCL18, CCL22, CCL15, CXCL12, and IL-6 in both the tumor site and peritumoral skin." (PMID 35409404, 2022). "Th17 cells are generated by tumor-derived IL1β and IL13, and accumulate in tumor tissues in response to various chemokines, including CCL2, CCL5, CCL20, CCL17, CCL22, and MIF, which are produced from tumor cells." (PMID 36211375, 2022). "Tumor-promoting TAMs, similarly to other TME cells, by the production of tumor-promoting factors, including VEGF, various cytokines (IL-10, CCL2, CCL17, CCL22, TGF-β), and matrix-degrading enzymes, facilitate the tumor invasion, angiogenesis, and spread." (PMID 34885122, 2021). "CCL17 and CCL22 induced by CD40 stimulation on B-cell leukemia cells have been shown to attract CCR4+ tumor-specific T cells." (PMID 33666760, 2021). "Next, to investigate the effect of the CCL17/CCR4 axis on PA invasion in vivo, a tumor-bearing NOD/SCID mouse model was utilized." (PMID 33664865, 2021). "Of these OPN, IL-33, CCL17, and MMP-9 were significantly reduced in the lung of 4T1 tumor-bearing mice treated with WECS." (PMID 34771120, 2021). "CircCHST15 located in the cytoplasm promoted tumor growth, down-regulated the expressions of miR-155-5p and miR-194-5p, and up-regulated the expressions of PD-L1, Ki-67, PCNA, CCL17, CCL22, IFN-γ, TNF-β, and IL-10." (PMID 33777742, 2021). "Activated eosinophils can secrete chemokines CXCL9, CXCL10, CCL17, and recruit CD4+T and CD8+T cells into the tumour microenvironment." (PMID 35003085, 2021). "It has been demonstrated that TAMs can produce various chemokines, including CCL17, CCL18, and CCL22, resulting in the attraction of Treg cells to tumor tissues and activation of CTLs." (PMID 34071550, 2021). "TAMs can produce various chemokines, such as CCL17, CCL18, and CCL22, which attract Treg cells to tumor sites, thereby impeding cytotoxic T cell activation." (PMID 33568167, 2021). "It was shown that 6 cytokines were upregulated more than 2-fold in 4T1 tumor-bearing mice compared to normal mice, namely OPN (osteopontin), CCL12 (chemokine (C-C motif) ligand 12), IL-33, CCL17, CCL6, and MMP-9." (PMID 34771120, 2021). "Their interaction with the BMDMs and tumor cells in the collagen-I matrix increased production of GM-CSF, G-CSF, IL-6, CCL2, CCL3, CCL4 and CCL12, and reduced production of IFN-β1, LIF, VEGF, CCL17, CXCL5 and CX3CL1." (PMID 34572807, 2021). "At the same time, CCL17 attenuates MDSCs via a pathway including IL-4 and CXCL17, downregulating tumor formation." (PMID 33670758, 2021). "An immune-suppressive tumor environment constituted by Tregs and M2 macrophages along with immunosuppressive mediators such as CCL17, CCL18, CCL22, and PD-L1 can assist tumor development and progression." (PMID 34937192, 2021). "CCL2 and C-C motif chemokine ligand 17 (CCL17) support tumour growth by recruiting CD4+ Treg cells and macrophages, while VEGF and MMP-9 stimulate angiogenesis and tumour cells migration." (PMID 34769447, 2021). "In fact, HRSCs produce Th-2 and T-reg chemoattractants, including CCL17/TARC, CCL22, CCL5, IL-4, IL-5, IL-10 and IL-13 and induce a functional reprogramming of tumour-infiltrating T cells skewing CD4+ differentiation toward Th-2 and T-reg phenotypes." (PMID 34298847, 2021).
tumor (continued). "For instance, CCL17 and CCL22, acting on CCR4, can directly recruit Th2 cells at the tumor site, thus participating in the development of cancers." (PMID 34777634, 2021). "They found that in tumor-bearing mice, sorafenib increased the number of TANs as well as CCL2 and CCL17 levels in the tumor." (PMID 32532960, 2020). "In our study, AdIL-17A transduction also directly upregulated CCR4 expression on tumor cells and enhanced expression of two CCR4 ligands, CCL17 and CCL22 in the lung." (PMID 32770025, 2020). "In human cancers, neutrophils exert tumor-promoting functions by producing a variety of factors, including HGF, CCL17, BMP2, among others." (PMID 32903528, 2020). "DCs can also secrete chemokines such as CCL2/3/4, CCL17, CCL19/21, and CXCL9/10/11 to recruit T cells and other cell subsets into the tumor sites." (PMID 33505304, 2020). "Among them, four genes, including APOL1, CCL17, RBP4, and KRT71 were selected in real-time PCR experiments between tumor samples and normal samples, which were found to be consistent with the expression trend in low- and high-risk groups." (PMID 33335850, 2020). "CCL17 and CCL22 are responsible for CCR4-dependent recruitment of Treg into the tumor niche, which enhances cancer immune evasion." (PMID 33182504, 2020). "In BCCs, the chemokines, CCL-17, CCL-18, and CCL-22 that recruit Tregs are overexpressed in the tumor islands and peritumoral skin." (PMID 31134198, 2019). "Factors such as CCL-2, CCL-5, CCL-17, CCL-22, CXCL-12, M-CSF, VEGF, and TGF-β synthesized by the tumor stroma aid in the recruitment of monocytes and subsets of T cells." (PMID 31134198, 2019). "Our results indicated that Plasmodium infection significantly inhibits the tumor secretions of GMCSF, IL-10, IL-6, CCL-17, and CCL-22 in vitro through exosomes-like vesicles released by infected red blood cells." (PMID 30979375, 2019). "Several reports have implicated the CCL17/22-CCR4 pathway and tumor-derived TGF-β in Treg recruitment and activation respectively in the tumor microenvironment, suggesting that inhibition of the CCL17/22-CCR4 pathway could substantially modulate the tumor accumulation of Tregs." (PMID 30979375, 2019). "TAMs exert a pro-tumor effect, inhibiting antitumor activities by secreting chemokines such as CCL17, CCL18 and CCL22, which attract Tregs cells to tumor sites, compromising the immune responses of CD8 + cytotoxic T cells." (PMID 31600917, 2019). "In the TME, the presence of CAFs and their secretion of CCL2, CCL5, and CCL17 as well as the polarizing cytokines IL-1, IL-6, IL-13, and IL-26 can favor a tumor promoting TH2 and TH17 immune response, as the expense of tumor protective TH1 response." (PMID 29545811, 2018). "By immunohistochemistry, we detected CCL17/TARC and its receptor CCR4 in the tumor cells of all MCC tissue samples analyzed." (PMID 30140381, 2018). "CCL17 and CCL22 expression was upregulated in several organs including lung, liver and brain of the tumor-bearing nude mice harboring these highly malignant tumors." (PMID 28415693, 2017). "CAFs are present within BCC stroma and associated with increased expression of chemokines involved in tumour progression and immunosuppression (CXCL12, CCL17)." (PMID 28987144, 2017). "These cells can enhance tumor angiogenesis, immunosuppression, tumor cell invasion and metastasis via the production of different cytokines and chemokines such as VEGF-A, CCL17/CCL22, and EGF." (PMID 28848446, 2017). "CXCL12, CCL17 and CCL22 play a role in the recruitment of T-regs to tumour sites and thereby inhibition of anti-tumour response." (PMID 28987144, 2017). "In the present study we investigated the effects of tumor-induced chemotaxis of Treg cells in vitro and the potential role of CCL22 or CCL17 in this process, and demonstrated that SSCC and NIP both significantly increased the chemotaxis of Treg cells." (PMID 26020249, 2015).
tumor (continued). "HPV-positive tumor tissue-derived cell cultures produced much higher levels of chemokines, namely CXCL9, CXCL10, CXCL12, CCL17 and CCL21." (PMID 25949860, 2015). "HPV-positive tumor tissue-derived cell cultures produced markedly higher levels of chemokines, namely CXCL9, CXCL10, CXCL12, CCL17 and CCL21, and slightly higher levels of the cytokines IL-2, IL-17, IL-23 and IFNγ." (PMID 25949860, 2015). "The levels of CCL17 (TARC), a ligand for CCR4, positively correlated with the numbers of tumor-infiltrating Th17, Th1 and CD8+ T lymphocytes." (PMID 25949860, 2015). "Several studies indicate that the tumor-expressed chemokines CCL22 and CCL17, which are ligands for CCR4, play a role in the recruitment and enrichment of Tregs." (PMID 23874342, 2013). "Studies have shown that several tumor-derived molecules are (CCL17, CC22, prostaglandin E2) involved in recruitment of CD4 Treg cells at tumor bed or periphery to induce tolerance against anti-tumor responses." (PMID 23152910, 2012). "At least some of the recruited cells are known to support tumor growth, such as macrophages (by CCL-2 and CCL-7) and T-regulatory cells (by CCL-17)." (PMID 22348096, 2012). "Previous evidence suggested that chemokine family members, such as CCL17 and CCL22, direct the movement of Tregs in tumor mass." (PMID 21655250, 2011). "Furthermore, the neutralization of CCL17 or CCL22 could prevent Treg cell infiltration to tumor." (PMID 20111717, 2010). "In the spleens of RLS40-bearing mice (tumor node > 1 cm3), the expression of markers corresponding to immunosuppressive phenotype were detected: in addition to PD-L1, the expression of CCL17 but not IL10 was detected." (PMID 40867260, 2025). "CCL17 regulates immune cell infiltration through its receptor CCR4, suppressing tumor progression." (PMID 40517358, 2025). "HRS cells secrete the chemokines CCL17 (also known as thymus and activation-regulated chemokine, TARC) and CCL22, which recruit CCR4-expressing Th2 cells and Tregs, promoting an immunosuppressive milieu that facilitates tumor survival." (PMID 40806636, 2025). "CCL17 and CCL22 also shape anti-tumour immunity, generally to the host’s detriment." (PMID 41291326, 2025). "Moreover, a significant correlation was established between the frequency of CCL17(+) or CCL22(+) cells and Foxp3(+) Tregs within tumor-infiltrating lymphocytes." (PMID 40134607, 2025). "Responders were always low in circulating CCL17 and IL-12p70, and generally, but not exclusively, higher in tumour MVD." (PMID 40295487, 2025). "We proposed that CCL17, with its chemotactic function, might recruit TAN into the tumor stroma to form a suppressive barrier." (PMID 38914802, 2024). "Some reports describe that the tumor immune escape can be driven by other immunosuppressive cytokine loops, including CCL22, CCL17, and CCL18 that are also secreted by macrophage for recruiting Treg cells and modulate the immune response during the tumorigenic process." (PMID 39061137, 2024). "The direct release of CCL17 by tumor cells has not yet been characterized, and the specific role of CCL17 in the interaction between tumor and tumor stroma in the TME remains undefined." (PMID 38914802, 2024). "However, there remains limited knowledge about the relationship between CD73, CCL17, and CCR4 within the tumor microenvironment in HCC." (PMID 38914802, 2024). "High-throughput single-cell RNA sequencing (scRNAseq) revealed that PAZ@Fe-MOF significantly reduced pro-tumorigenic M2-like macrophage populations at tumor sites and suppressed M2-type signaling pathways, such as ATF6-TGFBR1-SMAD3, as well as chemokines including CCL17, CCL22, and CCL24." (PMID 39033109, 2024). "Furthermore, STAT6D419 mutant tumor cells secrete more of the chemokine CCL17 upon IL-4 stimulation, and we are the first to provide evidence that this leads to increased CD4+ T-cell infiltration in rrDLBCL patient tumor biopsies." (PMID 38285120, 2024).
tumor (continued). "Its ligands, CCL17 and CCL22, are mainly released by tumor cells and TAMs." (PMID 39596815, 2024). "Moreover, our study found significantly elevated levels of the chemokine CCL17 (TARC) and the cytokine IL-6 in cHL patients at DIA, both of which are known to play crucial roles in modulating the tumor microenvironment." (PMID 39769007, 2024). "Mature mDCs specifically expressed CCR7, CCL17 and CCL22 to recruit infiltrating T cells, which transduced immune signals and recruits peripheral T cells in TME with strong migration and regulatory capabilities, thus playing an anti-tumor role." (PMID 39256364, 2024). "Therefore, mRNA expressions of chemokines CCL2, CCL17 and CCL22, as well as IL-6, IL-18, TNF-α and IFN-γ, in tumor tissues and H22 cells were detected by RT-qPCR." (PMID 36674931, 2023). "Similarly, CCL17 and CCL22 secreted by M2 macrophages and tumor cells recruit Tregs to the TME, thereby inhibiting anti-tumor immunity." (PMID 37568390, 2023). "Several chemokine ligands are expressed by the tumor: CCL17 and CCL22 promote recruitment of CCR4+ Tregs, while CXCR3—along with its ligands, CXCL9 and CXCL10—drives cytotoxic lymphocyte trafficking into the GBM tumor site." (PMID 37443804, 2023). "Combining our results and these established findings indicated a new axis of CCL17/22-CCR4-PI3K/AKT-IP3R rather than microenvironment stress led to the high level of GRP78 in tumor cells." (PMID 37658050, 2023). "Tumor cells secrete cytokines such as CCL5, CCL17 and CCL22 which Treg are chemotactic to." (PMID 37064113, 2023). "When administered to mice, the complex inhibited tumor growth, reduced signs of general toxicity, neurotoxicity and cardiotoxicity, increased the immune response (serum levels of IFN-γ, TNF-α and chemokines CCL4 and CCL17) and prolonged animal survival." (PMID 36672622, 2023). "Additionally, N2 inhibits the function of CD8+ T cells, contributes to tumor invasion and metastasis, and promotes tumor progression by recruiting macrophages and Tregs via CCL2 and CCL17." (PMID 37415162, 2023). "In addition, the presence of TARC/CCL17, MDC/CCL22 and MMP-2 in the tumor microenvironment was correlated with the modulation of OX40L and ICOSL in pDCs and their accumulation in the tumor." (PMID 37190135, 2023). "In a recent study, macrophage-derived CCL17 drove tumor invasion by acting on the CCL17/CCR4/mTORC1 pathway, suggesting that chemokines secreted by non-tumor cells may positively favor the invasiveness of PitNETs." (PMID 37958702, 2023). "RCC patients with an increased plasma CCL17/CCL22 ratio had decreased overall survival, and patients with increased expression of the receptor for these cytokines (CCR4) had worse overall survival in multiple tumor types, including RCC." (PMID 37568390, 2023). "The expression of Il4, Il13, Ccl11, Ccl17 and Ccl22 mRNA was increased two- to fourfold, whereas the expression of Tslp mRNA was not changed, in the skin lesions of Ddx5∆KC mice compared with Ddx5fl/fl mice at day 16 post-MC903 administration." (PMID 36271146, 2022). "However, other investigators and our team have found that using mouse models of melanoma, colon cancer, and pancreatic cancer increased CCL17 expression, induced local infiltration of CD8+ T cells into the tumor, and exerted antitumor effects." (PMID 35321241, 2022). "Importantly, CCR4 and its ligands CCL17 and CCL22 produced by TLS mature DCs, macrophages or tumor cells were shown to be involved in the Treg recruitment to the inflamed sites." (PMID 36566320, 2022). "An increase in CCL5 and CCL17 expressions stimulated by gene electrotransfer did not affect tumor growth." (PMID 36286054, 2022). "We grouped these samples by tumor type and examined FOXP3, CCL17, and CCL22 expression levels." (PMID 35025968, 2022). "Similarly, greater downregulation of tumor promotion proteins such as CCL17, CD70, and LAMP3 during dual therapy suggests that dual therapy further augments tumor suppression." (PMID 36572780, 2022).
tumor (continued). "Tumor cells did not separate into clear clusters and CCL17/22 expression was not biased to any particular region of the tumor cell UMAP." (PMID 35025968, 2022). "Plasmodium infection could inhibit tumor secretion of Granulocyte-Macrophage Colony-Stimulating Factor human (GMCSF), IL-10, IL-6, C-C class chemokines (CCL)-17, and CCL-22 through the release of exosome-like vesicles." (PMID 36004920, 2022). "This is probably because decreases in MDSCs in CCL17 TG mice leads to enhanced tumor immunity in the absence of Tregs." (PMID 33670758, 2021). "A substantial, but less pronounced reduction in Ccl17 was observed with LFPRLR SMO when analyzing the mixed cell population of the tumor rather than pure 4T1 cells (relative mean expression from 6 animals/group from 1.92 to 0.985)." (PMID 34375938, 2021). "Moreover, a positive correlation between the expression level of CCL17 and tumor size was observed in tumor-bearing NOD/SCID mice, which demonstrated the promoting function of M2-like TAM-derived CCL17 in invasive PAs." (PMID 33664865, 2021). "In the tumor tissues, CCL17 and CCL22 are mainly secreted by macrophages and tumor cells." (PMID 34885241, 2021). "Therefore, we determined the expression levels of CXCL-9, CXCL-10, CCL-17, and CCL-22 in tumor tissues." (PMID 34620867, 2021). "In addition, TAMs, monocytic-MDSCs, polymorphonuclear-MDSCs, and TANs can produce the CCR4 ligands CCL17 and CCL22 in tumor tissues, contributing to tumor progression by recruiting CCR4-expressing Treg cells." (PMID 34885241, 2021). "CCL17 and CCL22 are both produced by cancer cells in a tumor and by TAM." (PMID 33182504, 2020). "CCL17 and CCL22 are well established in recruiting Treg cells and favoring tumor outgrowth." (PMID 33252851, 2020). "Notably, administration of CCL17 and CCL22 antibodies led to a 30% inhibition in tumor weight relative to treatment with control antibody." (PMID 31911617, 2020). "TAMs are also able to express immune checkpoint modulators such as PD-L1 and various chemokines (C-C motif chemokine ligand 17 (CCL17), CCL22, C-X-C motif chemokine ligand 10 (CXCL10)) which attract effector/activated T regs that exert an immunosuppressive action and promote tumor growth." (PMID 33375467, 2020). "Using Apc1638N/+ CCL17eGFP/+ reporter knockin mice CCL17 expression could be detected in TAMs and DCs in tumors of AOM at significantly higher levels than in normal lamina propria of tumor bearing mice." (PMID 31681563, 2019). "We observed that Plasmodium infection significantly downregulated the expression of the chemokines CCL17 and CCL22 as well as their receptor, CCR4 in the tumor microenvironment further validating the reduction in the proportion of Tregs in the tumor tissues." (PMID 30979375, 2019). "Furthermore CCR4 (receptor for CCL17 and CCL22) antagonists have been shown to decrease the tumor-promoting environment." (PMID 30850664, 2019). "The expression of CCL17/TARC and CCR4 may constitute an autocrine or paracrine survival loop which contributes to the growth and survival of the tumor, and also mediates immune suppression through the recruitment of regulatory T cells." (PMID 30140381, 2018). "Once established, tumor-derived factors drive macrophages toward an immunosuppressive phenotype which impairs anti-tumor T cell activity, primarily through the secretion of anti-inflammatory cytokines/chemokines such as TGF-β, IL-10, CCL17, and CCL22." (PMID 30459812, 2018). "In the tumor microenvironment, a high expression of CCL17/TARC and CCR4 by MCC cells may contribute to the activation of inflammatory pathways and the promotion of tumor growth and immune suppression." (PMID 30140381, 2018). "The results indicated that Ccl17 (but not Ccl22) expression was significantly upregulated 10 wks following tumor cell inoculation." (PMID 28415693, 2017). "Moreover, TAM derived TGF-β, PGE2, IL-10, and cytokines such as CCL2, CCL17 and CCL18 recruit abundant Tregs to tumor cells." (PMID 29152078, 2017).